ENSG00000250264 (novel protein, TAP2-HLA-DOB readthrough)
Gene: Protein-coding gene on chromosome 6 (32,813,767 to 32,838,822, reverse strand). Ensembl gene ENSG00000250264.
Genetic constraint (gnomAD): Loss-of-function variants: 59 observed, 91.93 expected, observed/expected ratio (o/e) 0.64, 90% interval 0.52 to 0.8. Missense variants: 930 observed, 1,077 expected, observed/expected ratio (o/e) 0.86, 90% interval 0.82 to 0.91. Synonymous variants: 385 observed, 455.7 expected, observed/expected ratio (o/e) 0.84, 90% interval 0.78 to 0.92.